ZNF705B (zinc finger protein 705B)
Description:
May be involved in transcriptional regulation.
Tractability: No criterion of Open Targets' tractability assessment is met for any kind of drug.
Gene: Protein-coding gene on chromosome 8 (7,926,337 to 7,952,413, forward strand). Ensembl gene ENSG00000215356.
Subcellular location: Nucleus
Gene Ontology:
Molecular function: DNA-binding transcription factor activity, RNA polymerase II-specific; RNA polymerase II transcription regulatory region sequence-specific DNA binding; sequence-specific double-stranded DNA binding
Biological process: regulation of transcription by RNA polymerase II; regulation of DNA-templated transcription
Cellular component: nucleus
Homologues: Orthologues: mouse Zfp78 (35% identical), Drosophila melanogaster CG3281 (23% identical), Drosophila melanogaster CG2712 (21% identical), Drosophila melanogaster Phs (19% identical). Paralogues in human: ZNF705D (99% identical), ZNF705A (95% identical), ZNF705G (92% identical), ZNF596 (53% identical), ZFP90 (42% identical), ZNF555 (37% identical), ZNF266 (37% identical), ZNF77 (36% identical), ZFP69B (36% identical), ZNF805 (36% identical), ZNF599 (36% identical), ZNF614 (36% identical), and 50 more.